TRPV1 (transient receptor potential cation channel subfamily V member 1)
Diseases named in the same sentence as TRPV1 in open-access papers (continued):
Sharing a sentence is not in itself a finding about the gene and the disease.
psoriasis (continued). "Overexpression of TRPV1 was found to positively correlate with itching in psoriasis and dermatitis." (PMID 41226679, 2025). "TRPV1 has long been studied as a clinical target for psoriasis treatment." (PMID 38474002, 2024). "Thus, the loss of ASIC3 in mice is as effective as nociceptor ablation in ameliorating psoriatic inflammation, underscoring the unequivocal functional significance of ASIC3 in TRPV1+ nociceptors in psoriasis pathogenesis." (PMID 38902277, 2024). "Overexpression, gain of function, and activation of channels, including nAChR, TRPV1, TRPV3, TRPV4, TRPM4, and ANO1 in keratinocytes, as well as TRPV1, nAChR, Kv1.3, and KCa3.1 in immune cells, have been associated with the induction of psoriasis." (PMID 38474002, 2024). "Further research demonstrated a close relationship between TRPV1 and the pathogenesis of psoriasis." (PMID 36874007, 2023). "A study found a positive correlation between TRPV1 overexpression and psoriasis itching." (PMID 36874007, 2023). "In addition, TRPV1+ nociceptors have been shown to play a role in psoriasis, barrier recovery, AD, and allergic contact dermatitis (ACD)." (PMID 34200205, 2021). "Thus, we have defined the TRPV1+ sensory neurons/CGRP/IL-23-producing cells/γδ T cell axis that provides a critical neuron-immune response at the early stage of IMQ-induced psoriasis inflammation." (PMID 34745116, 2021). "In a recent study using a transgenic experimental mouse model, it was found that peripheral TRPV1+ neuron activation, by isolated stimulation, is able to trigger psoriasis-like dermatitis and type 17 inflammation by local TCR γδ T cells, which can be blocked by botulinum neurotoxin A (BoNT/A)." (PMID 33133059, 2020). "Pharmacological ablation of TRPV1+ fibers result in significantly alleviated psoriasis-like lesions accompanied by decreased expression of IL-23, IL-17, and IL-22 and decreased recruitment of inflammatory cells in the murine model of psoriasiform skin inflammation." (PMID 33133059, 2020). "In the skin, TRPV1 is present on the membranes of keratinocytes, mast cells, Langerhans cells, sebocytes, sweat gland cells, and hair follicles, and it plays an important role in skin inflammation, pain, and itching, contributing significantly to the pathogenesis of dermatitis and psoriasis." (PMID 41226679, 2025). "Here, for the first time, the peptide TRPV1 blocker, HCRG21, was used to treat chronic inflammatory skin conditions, psoriasis, and ACD using IMQ- and DNFB-induced CD-1 mouse models, respectively." (PMID 41226679, 2025). "Both the inositol triphosphate receptor and TRPV1 in the internal calcium reservoirs play important roles in PAR2-evoked calcium release and subsequent skin inflammation in psoriasis." (PMID 38474002, 2024). "Specifically, peripheral blood mononuclear cells from individuals with psoriasis exhibit elevated expression of TRP channels such as TRPM2 and TRPV1 and decreased expression of TRPM4, TRPM7, TRPV3, TRPV4, and TRPC6." (PMID 38474002, 2024). "Blockade of TRPV1 in DRG was considered as a potential method in cardioprotection, irritable bowel syndrome, psoriasis, prostatitis, neuropathic pain, cystitis." (PMID 36919561, 2023). "In this context, TRPV1 was also found to contribute to adverse pain-mediating effects in an in vitro model of psoralen UVA (PUVA) therapy used to treat vitiligo, psoriasis, eczema and mycosis fungoides." (PMID 36552866, 2022). "Analysis of skin biopsies revealed that TRPV2 was downregulated in itchy skin regions of psoriasis patients, while FAAH1, TRPV1 and TRPV3 were upregulated." (PMID 36552866, 2022). "Previous studies demonstrated that the gene expression levels of TRPV1, TRPM8, and TRPV3 were significantly elevated in pruritic skin with psoriasis." (PMID 33182442, 2020). "Previous findings indicate that TRPV1-expressing neurons control cutaneous immune responses to pathogens 62,63, as well as skin inflammation in the IMQ animal model of psoriasis." (PMID 33204332, 2020).
psoriasis (continued). "The presence of psoriasis, as well as the irradiation of keratinocytes with UVA/B radiation, was accompanied by an increased expression of the receptors tested (CB1/2 and TRPV1)." (PMID 32121131, 2020). "These channels have also shown different contributions to various psoriatic symptoms, with TRPV1 and TRPC4 being detrimental and TRPA1 being beneficial for psoriasis in preclinical studies 11,12,18,19." (PMID 33204332, 2020). "Using imiquimod-induced psoriasis model mice, they demonstrated that TRPC4 was expressed in a subset of peptidergic neurons expressing TRPV1 that innervate the skin." (PMID 33182442, 2020). "In summary, we reported that RvD3 significantly alleviated psoriasiform itch and skin inflammation in the IMQ-animal model of psoriasis via activation of the ALX/FPR2 receptor, inhibition of TRPV1 activity, and reduction in CGRP release." (PMID 33204332, 2020). "This denervation treatment of TRPV1+ nociceptive terminals significantly reduced splenomegaly of the IMQ-treated Asic3+/+ mice, indicating that TRPV1+ nociceptive innervation regulates the global inflammatory response in psoriasis." (PMID 38902277, 2024). "Notably, increased expression of TRPV1 was observed in the skin of psoriatic patients and in a mouse model of IMQ-induced psoriasis." (PMID 38474002, 2024). "In preclinical models of psoriasis, resolving D3 (RvD3) derived from ω-3 fatty acids prevented the development of both psoriasis-form itch and skin inflammation with the concomitant decreased expression of CGRP in TRPV1+ neurons." (PMID 36874007, 2023). "As shown recently by others and our group, TRPV1 and TRPA1 have previously been shown to also play important roles in pathological skin conditions, such as pruritus, atopic dermatitis and psoriasis." (PMID 35457056, 2022). "The abnormal activation of TRPV1/TRPA1 channels can result in pruritus and hyperalgesia, and accounts for the clinical phenomena experienced by approximately 60%-90% of patients with psoriasis, such as itching, skin pain, and discomfort." (PMID 34745116, 2021). "The TRPV1 and TRPA1 channels are at the core of the inflammatory process that occurs in various cutaneous neurogenic disorders that are pruritic diseases, such as psoriasis, AD, and Netherton syndrome." (PMID 28364279, 2017). "Hence, this suggests that TRPV1 does not have a major role in this model of psoriasis and the cutaneous discomfort." (PMID 30204499, 2019). "However, in Asic3−/− mice, the chemical denervation of TRPV1+ nociceptors failed to further alleviate splenomegaly in the psoriasis model, arguing for the essential role of ASIC3 in the TRPV1+ nociceptor-mediated regulation." (PMID 38902277, 2024).
atherosclerosis (29 papers, 2013 to 2026). A disease characterized by the build-up of fatty material and calcium deposition in the arterial wall resulting in partial or complete occlusion of the arterial lumen. "Immunohistochemical staining for TRPV1 reveals positive signals confined mainly to areas of macrophages in atherosclerotic lesions of apolipoprotein E-deficient mice (ApoE–/–, a model of atherosclerosis-prone mice)." (PMID 33613196, 2020). "This study employed a murine model of atherosclerosis (AS) and Transient Receptor Potential Vanilloid 1 (TRPV1)-deficient AS mice to ascertain whether TRPV1 exerts an influence on AS by modulating aortic aging." (PMID 42033162, 2026). "The transient receptor potential vanilloid type 1 (TRPV1) is crucial in the pathogenesis of atherosclerosis; yet its role and underlying mechanism in the formation of macrophage foam cells remain unclear." (PMID 23878415, 2013). "Recently, we reported that deletion of TRPV1 worsened atherosclerotic lesions in apolipoprotein E-deficient mice (ApoE−/−, a model of atherosclerosis-prone mice), so TRPV1 may have a role in atherogenesis." (PMID 23878415, 2013). "Mechanistic insights into capsaicin’s actions involving TRPV1 and PPARγ pathways provide further rationale for exploring its clinical applications in managing atherosclerosis and related complications." (PMID 39339767, 2024). "Transient receptor potential vanilloid 1 (TRPV1) was reported to regulate autophagy to protect against foam cell formation in atherosclerosis." (PMID 36720919, 2023). "Though it is beyond the scope of this review, it should be mentioned briefly that TRPV1 has also been implicated in the proliferation and migration of vascular smooth muscle cells, linking TRPV1 to atherosclerosis and other vascular diseases." (PMID 37240118, 2023). "TRPV1 activity reduces lipid storage, which is a promising therapeutic tool for atherosclerosis, as the use of copper sulfide (CuS) nanoparticles targeting TRPV1 channels in vascular smooth muscle cells helps to attenuate fat accumulation." (PMID 38328578, 2023). "TRPV1 was reported to regulate autophagy to protect against foam cell formation and reduce the release of inflammatory factors in atherosclerosis." (PMID 35115924, 2021). "Most in vivo studies targeting TRPV1 in animal models of atherosclerosis use dietary capsaicin treatment to achieve improvement either in atherosclerotic plaque reduction or in the accompanying inflammation." (PMID 32586044, 2020). "Altogether, these studies indicate that TRPC3/C6 and TRPV1/V4 in particular are involved in different aspects of atherosclerosis progression, while more data are needed to confirm the role of other TRPC and TRPV isoforms." (PMID 32854408, 2020). "Although some progress has been made, the clinical application of TRPV1 in the protection of atherosclerosis needs to be further explored." (PMID 32274960, 2020). "Although capsaicin can activate TRPV1 channels and reduce lipid storage and atherosclerosis formation, its chronic toxicity limits its clinical application." (PMID 32274960, 2020). "TRPV1 modulates the physiological and pathophysiological functions of vascular endothelial cells; its role in atherosclerosis is clearly demonstrated in preclinical studies." (PMID 32586044, 2020). "TRPV1 activation also inhibited VSMCs proliferation in an atherosclerosis context and prevented inflammation and oxidation." (PMID 32854408, 2020). "In summary, TRPV1 activation can improve atherosclerosis through a variety of mechanisms, but its clinical application is focused on mainly analgesia." (PMID 32274960, 2020). "Regarding in vivo atheroprotective effects, chili pepper triggered TRPV1 activation to reduce vascular lipid accumulation and attenuate atherosclerosis in ApoE−/− mice fed an HFD." (PMID 30423840, 2018). "Here, we develop a CuS NPs-based switch for photothermal activation of TRPV1 signaling to impede the progression of atherosclerosis." (PMID 29335450, 2018).
atherosclerosis (continued). "Treatment with oxLDL, the most important modulator in the development of atherosclerosis, increased TRPV1 channel activity in BMDMs, as evidenced by a TRPV1-mediated increase in [Ca2+]i level to a profile similar to that evoked by TRPV1 agonists." (PMID 23878415, 2013). "Our previous study demonstrated that chronic treatment of ApoE−/− mice with the TRPV1 agonist evodiamine alleviated hyperlipidemia, systemic inflammation, hepatic macrovesicular steatosis, and atherosclerosis." (PMID 23878415, 2013). "Given the established role of TRPV1–CGRP signaling within NICIs in atherosclerosis, it is plausible that IL-1β blockade might also dampen neurogenic inflammation in vascular lesions." (PMID 40977707, 2025). "Furthermore, while some advancements have been achieved, the clinical utilization of TRPV1 in the prevention of atherosclerosis necessitates further investigation." (PMID 40029381, 2025). "These underscore the potential role of TRPV1 in mitigating high-fat diet-induced atherosclerosis." (PMID 39965247, 2025). "constructed a switch for photothermal activation of the TRPV1 signaling pathway by combining copper sulfide (CuS) nanoparticles with TRPV1 monoclonal antibodies (CuS-TRPV1 NPs) to alleviate atherosclerosis through nanoparticle-mediated photothermal modulation of TRPV1." (PMID 37674191, 2023). "TRPV1 activation protected from atherosclerosis by eNOS production and induced angiogenesis." (PMID 34282193, 2021). "However, further transcriptomics and proteomics studies would be essential to elucidate all players of the beneficial effects of TRPV1 and/or capsaicin-sensitive sensory nerve activation in atherosclerosis and CAD." (PMID 32586044, 2020). "Notably, in atherosclerosis, the activation of TRPV1 can regulate lipid metabolism, reduce foam cell formation, protect endothelial cells, inhibit smooth muscle cell proliferation and inhibit inflammation and oxidation." (PMID 32274960, 2020). "Thus, activation of TRPV1 by agonists plays a protective role against foam-cell formation and development of atherosclerosis." (PMID 33613196, 2020). "TRPV1 modulates the inflammatory response of endothelial cells, therefore, activation of TRPV1 should be considered as a new potential therapeutic target for the treatment of inflammatory vascular diseases, especially for atherosclerosis." (PMID 32586044, 2020). "TRPVs: Compelling evidence points to the fact that TRPV1 and V4 play a role in atherosclerosis." (PMID 32854408, 2020). "In case of high-fat diet, TRPV1 could be a therapeutic target for attenuation of atherosclerosis development." (PMID 31263706, 2019). "TRPV1 displays a preventive role in atherosclerosis development." (PMID 31263706, 2019). "In addition, several lines of evidence support the ameliorative role of TRPV1 in myocardial infarction as found in atherosclerosis." (PMID 26482920, 2016). "In apolipoprotein E-deficient mice, evodiamine significantly reduced atherosclerosis, hyperlipidemia, and systemic inflammation and this beneficially therapeutic effect was not seen in ApoE−/− mice that lack TRPV1, suggesting that TRPV1 curbs the development of atherosclerosis." (PMID 36589466, 2022). "Second, activation of TRPV1 could reduce vascular lipid accumulation and attenuate atherosclerosis." (PMID 34229688, 2021). "They provided evidence that TRPV1 may have a role in human platelets linking inflammatory mediators, such as 12- and 15-hydroxyeicosatetraenoic acid produced in atherosclerotic plaques, and platelet activation during atherosclerosis." (PMID 35011580, 2021). "Consistently, capsaicin stimulated endothelial TRPV1 to recruit the downstream PKA/UCP signaling cascade and thus mitigate mitochondrial dysfunction and restore coronary vasodilation and myocardial perfusion in atherosclerosis-prone apoliprotein E-deficient mice." (PMID 32471282, 2020). "Thus, TRPV1 may play an important role in the development of atherosclerosis." (PMID 23878415, 2013).
atherosclerosis (continued). "TRPV1 agonizts promote cholesterol efflux by upregulating the efflux of ABCA1 and ABCG1 in macrophages through liver X receptor α-dependent regulation of transcription in the pathogenesis of atherosclerosis." (PMID 36720919, 2023). "In the context of atherosclerosis, inflammatory cues such as LPS/TLR4 signaling, local acidosis, and endogenous lipid mediators, including capsaisin, anandamide (AEA) and N-arachidonoyl dopamine (NADA), sensitize TRPV1 channels expressed on perivascular sensory afferents." (PMID 40977707, 2025). "While direct evidence for IL-1β–TRPV1 crosstalk in atherosclerosis is lacking, future investigations could reveal whether sensory neuroimmune desensitization contributes to the plaque-stabilizing effects of anti-cytokine therapy." (PMID 40977707, 2025). "This alternative non-pharmacological way of TRPV1 activation may represent a novel therapeutic tool to improve atherosclerosis." (PMID 32586044, 2020).
melanoma (29 papers, 2012 to 2025). A malignant, usually aggressive tumor composed of atypical, neoplastic melanocytes. "TRPV1 is upregulated in certain melanoma lines and may promote inflammation-associated carcinogenesis by modulating the tumor microenvironment and oxidative stress responses." (PMID 40869148, 2025). "TRPV1 and TRPV4, members of the vanilloid subfamily, have been implicated in melanoma biology, though their roles remain somewhat controversial." (PMID 40869148, 2025). "TRPV1 is a potential tumor suppressor in melanoma, and the higher the expression, the better the prognosis." (PMID 40007993, 2025). "TRPM1 has been implicated in tumor suppression, while TRPM7, TRPV1, and TRPV4 have been observed to function as both melanoma suppressors and oncogenic drivers, modulating proliferation, apoptosis and metastasis." (PMID 40869148, 2025). "It was found that the expression of TRPV1 in melanoma tissues and cell lines was significantly lower than that in nevus tissues and normal melanocytes." (PMID 40007993, 2025). "TRPM1 is implicated as a tumor suppressor, whereas TRPM7, TRPV1, and TRPV4 often function as both melanoma suppressor or oncogenic drivers, modulating proliferation, apoptosis, and metastasis." (PMID 40869148, 2025). "In consideration of the findings, it can be posited that TRPV1 functions as a tumor suppressor in melanoma, thereby constraining proliferation and inducing the programmed cell death of tumor cells." (PMID 40869148, 2025). "With a sufficient supply of Ca2+ from CaCO3, CBD activates TRPV1 to induce melanoma apoptosis via the “Ca2+ influx-NFATc1-ATF3” pathway." (PMID 37198657, 2023). "For example, human melanoma samples were found to have increased TRPV1-expressing neuronal innervation." (PMID 37371563, 2023). "When co-cultured with B16F10 murine melanoma cells, TRPV1-positive nociceptors directly extended neurites toward the cancer cells." (PMID 37371563, 2023). "TRPV1 protein expression was demonstrated in melanoma, but it was also detected in benign nevi; therefore, it cannot differentiate between benign and malignant melanocytic proliferations." (PMID 37240443, 2023). "When co-cultured, TRPV1+ nociceptors directly extended neurites towards the B16F10-eGFP melanoma cells, and the average length of neurites increased, whereas the overall neuronal arborization or branching decreased." (PMID 36323780, 2022). "As these clinical data suggested increased innervation of melanomas, we tested for the presence of nociceptor neurons by assessing TRPV1+ neurons in biopsies from patients with melanoma." (PMID 36323780, 2022). "Recent studies have reported that TRPM8 and TRPA1 exhibit abnormal expression in melanoma cell lines, and functional TRPV1, TRPM8, and TRPA1 have been found in malignant uveal melanoma tissues and cell lines." (PMID 34831352, 2021). "In melanoma patients, the median transcript levels of genes expressed in sensory nerves [Nav1.8, TRPV1 and vasoactive intestinal peptide (VIP)] were used to stratify 21437 patient tumour transcriptomes into high and low expression for each gene." (PMID 32691511, 2020). "In melanoma tissues, decreased TRPV1 expression has been observed when compared to normal melanocytes, and TRPV1 overexpression inhibits melanoma growth via Ca2+ signaling." (PMID 32604833, 2020).